CASP1 (caspase 1)
Diseases named in the same sentence as CASP1 in open-access papers (continued):
Sharing a sentence is not in itself a finding about the gene and the disease.
colitis (continued). "The absence of AIM2 affected caspase-1 activation and the production of IL-1β and IL-18, whilst also making mice highly susceptible to DSS-induced colitis associated with microbial dysbiosis." (PMID 39684769, 2024). "APS can also downregulate the expression of NLRP3, caspase-1, and ASC in colon tissue, prevent the activation of the NLRP3 inflammasome, thereby reducing the expression of IL-18 and IL-1β and alleviating DSS-induced colon inflammation." (PMID 37849728, 2023). "In colitis-associated cancer models, mice lacking ASC, caspase-1, or NLRP3 show more severe colitis and accentuated tumorigenesis." (PMID 36932407, 2023). "This illustrated that both blockade of caspase-1-mediated pyroptosis and T.s intervention could ameliorate DSS-induced colitis in mice." (PMID 37580819, 2023). "Furthermore, the anti-colitis activity of shionone was also observed with a reduction in inflammation and inflammatory factors such as NLRP3, caspase 1, and IL-1β in the colon." (PMID 38202771, 2023). "In addition, our study found that Forsythia suspensa extract can inhibit the protein and gene expression levels of NLRP3, ASC, Caspase-1 and GSDMD in colitis mice." (PMID 35326124, 2022). "It is recently found that 10-hydroxy-2-decenoic acid (10-HDA), the most abundant fatty acid and major lipid component in royal jelly, alleviated DSS-induced colitis and enhancing colonic barrier function by regulating the NLRP3/caspase-1/GSDMD-mediated pyroptotic pathway." (PMID 36505474, 2022). "In line with previous studies showing a role for NLRP3 inflammasome in DSS colitis etiopathogenesis, we found an increased expression of both IL1B mRNA and inflammasome components, as well as protein levels of pro-Caspase-1, in colonic tissue of DSS-treated mice." (PMID 35327334, 2022). "The monitoring of NLRP3 inflammasome protein levels in the inflamed colon tissue of Kunming mice (colitis model), by Western blot analysis, after sinapic acid treatment for 7 days, have shown a reduction in the amounts of NLRP3, ASC, IL-1β, and caspase-1 proteins." (PMID 35276849, 2022). "We detected an increase in caspase-1 p45 and p20 expression in some, but not all, brains isolated from mice with ongoing colitis." (PMID 34758843, 2021). "Caspase-1 KO mice showed a reduction of acute and chronic DSS-induced colitis." (PMID 33143375, 2020). "The western blot results of the in vitro experiments showed that treatment with MCC950 significantly reduced the active caspase-1 p10 and IL-1β in BMDMs and colon explants suggesting that MCC950 inhibits the activation of NLRP3 inflammasome in the colitis model." (PMID 29872077, 2018). "With regard to non-canonical NLRP3 inflammasome activation, the majority of current data suggest that caspase-11-dependent NLRP3 activation, although dispensable for caspase-1-inflammasome assembly, contributes to protection against DSS-induced colitis regulating the epithelial barrier integrity." (PMID 28179906, 2017). "Furthermore, 3-MA also attenuated the inhibitory effect of HU 308 on Casp-1 p20/Casp-1 p45 ratio and proIL-1β in colon from DSS-induced colitis mice." (PMID 27611972, 2016). "Indeed, inhibition of caspase-1 with belnacasan obviously reduced the mature IL-1β level in colon tissue and largely prevented the deteriorating role of DCA in the DSS-induced colitis." (PMID 27965665, 2016). "The tumor-suppressing function of inflammasomes does not always correlate with their role in promoting or suppressing DSS-induced inflammation; rather some studies have reported that Casp1−/− and Nlrp3−/− mice have decreased DSS-induced inflammation and colitis." (PMID 24474192, 2014). "Additionally, homozygous knock-out of NLRP3 and caspase-1 genes, or inhibition of caspase-1 by a specific inhibitor, protects mice from DSS-induced colitis." (PMID 23915129, 2013).
colitis (continued). "Western blotting analysis revealed that expression of the inflammasome complex proteins such as NLRP3 and ASC are not changed during colitis, but procaspase-1 is increased in its expression and cleaved into caspase-1 in DSS- and DSS+dTPP-treated mice." (PMID 23915129, 2013). "Mice lacking caspase-1 or NLRC4 exhibited greater proliferation of colonic epithelial cells and decreased apoptosis of tumor cells, which led to an increase in tumor formation in colitis-associated colorectal cancer models." (PMID 40141358, 2025). "Activation of caspase-1, a key effector of the inflammasome complex, has been observed to contribute to CD4 T cell depletion during HIV infection, while blocking IL-18 signaling in T cells may exacerbate disease severity in murine colitis models." (PMID 40530419, 2025). "Taken together, KLPJ-mediated colitis occurs through caspase-1/11, but not NLRC4 or NLRP3." (PMID 36436756, 2023). "Recently, a number of independent studies suggested that proper intracellular NLRP3, Caspase-1, ASC and IL-1β levels are a prerequisite to maintain intestinal epithelial integrity, limit pathogen colonization and prevent systemic dispersion of commensal bacteria and severe colitis." (PMID 37891577, 2023). "In addition, the impact of apigenin on colitis was not affected by the absence of caspase-1/11 or ASC." (PMID 36090968, 2022). "In addition, two recent studies showed that a synthetic benzimidazole compound and fumigaclavine C, a fungal metabolite exerted anti-inflammatory effects in mice with colitis induced by dextran sulfate sodium (DSS), through the inhibition of caspase-1 activation." (PMID 30559669, 2018). "Therefore, we confirmed that oroxylin A could down-regulate the activation of NLRP3 inflammasome, with decreased levels of caspase-1, IL-1β and NLRP3 in colon samples of DSS-induced colitis mice." (PMID 28938606, 2017). "Nonetheless, the phenotype of these knockout mice did not change after cohousing of these mice with WT mice, suggesting that the differences in gut microbes, if any, did not contribute to the high sensitivity to OXA-induced colitis in NLRP3−/− or caspase-1−/− mice." (PMID 27966619, 2016). "Therefore, we believe that the difference in gut microbes, if any, did not contribute to high sensitivity to OXA-induced colitis in NLRP3−/− or caspase-1−/− mice." (PMID 27966619, 2016). "Although deficiency in other inflammasome components, including ASC, caspase-1, and IL-18, also led to dysbiosis and exacerbated colitis, deficiency in NLRC4, NLRP10, NLRP12, and AIM2 had no impact on the susceptibility of WT mice to colitis upon cohousing." (PMID 26925061, 2016). "For example, 2 groups independently reported that the absence of NLRP3 and caspase-1 attenuated chemical-induced colitis in mice, whereas other groups have reported that different inflammasome knockout (KO) mice are more sensitive to chemical-induced colitis and tumorigenesis." (PMID 26689911, 2015). "In light of this discovery, the contribution of caspase-11 to the conflicting phenotypes that have been reported for caspase-1–null mice during DSS-induced colitis need to be re-examined, because capase-1 has been attributed with both protective and detrimental roles in the pathogenesis of colitis." (PMID 25548224, 2015). "However, dextran sodium sulfate (DSS)-induced colitis could be mediated by the NLRP3 inflammasome activation-induced caspase-1 cleavage and IL-1β secretion, and mice lacking NLRP3 were significantly protected from colitis." (PMID 30696442, 2019). "However, we believe that contributions of pro-IL-1β and pro-IL-18 downregulation to colitis are none or negligible because impact of Rev-erbα on inflammasome activation (i.e., activation of caspase-1 and maturation of IL-1β) and experimental colitis is highly Nlrp3-dependent." (PMID 30315268, 2018). "Therefore, their anti-inflammatory effects on colitis may not result merely from the inhibition of caspase-1." (PMID 30559669, 2018).
colitis (continued). "However, this phenotype was specific to colorectal cancer and not DSS colitis indicating that increased colonic inflammation was not the driving force for the enhanced tumorigenesis seen in Nlrc4−/− and caspase-1−/− mice and instead was likely due to a cell intrinsic mechanism." (PMID 24273542, 2013). "One of these agents is decursinol angelate (DA), a natural compound that was found to inhibit the activation of the NLRP3 inflammasome—without caspase-1 activation—leading to reduced pyroptosis and inflammation in the colon in DSS-induced colitis in mice." (PMID 40869366, 2025). "A severe enhancement in acute and recurrent colitis as well as the progression of CAC was observed in rodents lacking NLRP3, Pycard, and Casp-1, which was partially induced by suppressed IL1 and IL18." (PMID 38892354, 2024). "In fact, Bauer and co-workers reported that the administration of Pralnacasan, a potent and non-peptide inhibitor for caspase-1, prevented DSS-induced colitis." (PMID 39684769, 2024). "The researchers showed that NOR alleviated colitis and reduced the levels of NLRP3, cleaved caspase-1 and IL-1β in colons of the mice." (PMID 36090968, 2022). "In this model the pro-inflammatory role of IL-1β seems to be non-redundant as treatment with a CASP1 or a NLRP3 inhibitor ameliorated established disease and prevented or delayed development of spontaneous colitis." (PMID 34344313, 2021). "Apigenin showed a protective effect against colitis in mice via NLRP6 signalling, which still happened in the absence of caspase 1/11 or Asc, suggesting that an alternative mechanism to the classical inflammasome pathways was involved." (PMID 33682108, 2021). "The results of this study indicated that canonical caspase-1 activation, but not that of caspase-11, was responsible for the exacerbation of DSS-induced colitis." (PMID 33143375, 2020). "The levels of cleaved (activated) caspase-1 and mature IL-1β were reduced by E. faecalis in the colon tissues of mice with DSS-induced colitis compared to PBS control in wild type mice, but not in NLRP3-deficient mice." (PMID 30823406, 2019). "Without Caspase-1, mice succumb to bacteremia sooner and have higher bacterial loads in the MLN, liver and spleen in the typhoid model of infection, and more colitis accompanied by increased bacterial mucosal infiltration." (PMID 24381573, 2013).
atherosclerosis (100 papers, 2009 to 2025). A disease characterized by the build-up of fatty material and calcium deposition in the arterial wall resulting in partial or complete occlusion of the arterial lumen. "In mice, Caspase 1 deficiency correlates with a reduction in atherosclerosis, as well as reducing endothelial cell activation and monocyte recruitment to the plaque." (PMID 38255935, 2024). "Herein, we demonstrated the causative effect of caspase-1 activation in HIV-1-associated atherosclerosis using HIV-1 transgenic mice under an atherogenic background and diet." (PMID 37629052, 2023). "Together, the results reported here further highlight the important role of caspase-1 in HIV-associated atherosclerosis." (PMID 37629052, 2023). "This activation leads to caspase-1-mediated maturation and secretion of IL-1β, further promoting the inflammatory response associated with atherosclerosis." (PMID 37900059, 2023). "The molecular pathways involved in accelerated HIV-associated atherosclerosis were explored using both global and hematopoietic cell deficiency of caspase-1 in an HIV transgenic mouse model with an atherogenic background." (PMID 37629052, 2023). "Our previous studies demonstrated that caspase-1 activation in myeloid cells was associated with HIV-associated atherosclerosis in HIV transgenic (Tg26+/−/ApoE−/−) mice and people with HIV." (PMID 37629052, 2023). "Previously, we documented that caspase-1 activation in myeloid cells was linked with HIV-associated atherosclerosis in mice and people with HIV." (PMID 37629052, 2023). "We reported that hyperlipidemia drives early atherosclerosis via disease risk sensing caspase 1-inflammasome pathway." (PMID 35320939, 2022). "Important functional molecules that result in pyroptosis, including NLRP3, AIM2, and caspase-1, are abundantly expressed and activated in atherosclerosis and are associated with the occurrence, accumulation, and destabilization of atherosclerotic plaques." (PMID 35096837, 2021). "Recent studies found that caspase-1 associated pyroptosis occurs in VSMCs and its activation potentiated the progression of atherosclerosis." (PMID 33981234, 2021). "Atherosclerosis was ameliorated upon deletion of the Casp1 gene in apolipoprotein E deficiency (ApoE−/−) mice (also a widely used atherosclerosis mouse model)." (PMID 33535473, 2021). "Moreover, caspase-1 deficiency improved the phenotype in atherosclerosis-prone apolipoprotein E-deficient (Apoe−/−) mice displaying poor lipoprotein clearance, resulting in atherosclerotic plaques." (PMID 38824481, 2024). "Taken together, these results highlight the atherogenic role of caspase-1 in HIV-associated macrophage activation and atherosclerosis and indicate that therapeutic inhibition of caspase-1 may have a beneficial effect on treating HIV-associated atherosclerosis." (PMID 37629052, 2023). "Here, we mechanistically examined the direct effect of caspase-1 on HIV-associated atherosclerosis." (PMID 37629052, 2023). "In addition, a genetic study documented that caspase 1 deficiency ameliorated atherosclerosis in ApoE−/− mice." (PMID 35641492, 2022). "Studies have shown that ApoE-/-Caspase-1/11-/- double deficient mice have fewer signs of atherosclerosis than ApoE-/- mice, meaning that inflammasome activation is also a key factor in the inflammatory response during atherosclerosis." (PMID 24312444, 2013). "Increasing evidence indicates that IL-1 is involved in both development of atherosclerosis and cardiovascular risk, and CASP1 might play a key role in the proatherogenic effects mediated by IL-1β." (PMID 20184726, 2010).
atherosclerosis (continued). "P2X7 expression was increased in human and murine atherosclerotic lesions and deficiency in p2x7 led to reduced caspase-1 and inflammasome activation upon stimulation with LPS and oxLDL, respectively, and reduced atherosclerotic lesions and macrophage recruitment in murine models of atherosclerosis." (PMID 37239938, 2023). "Additionally, caspase-1 deficiency decreases atherosclerosis in apolipoprotein E-null mice." (PMID 29416034, 2018). "The activation of the NLRP3 inflammasome leads to the cleavage of procaspase-1 into active caspase-1, which in turn promotes the maturation and secretion of proinflammatory cytokines that contribute to atherosclerosis." (PMID 40966231, 2025). "Pyroptosis, which is mediated by caspase-1-dependent inflammasome activation and gasdermin proteins, amplifies local and systemic inflammation, accelerating atherosclerosis by releasing inflammatory cytokines such as interleukin (IL)-1β and IL-18." (PMID 39898976, 2025). "For example, a study found that two ferroptosis-related proteins, PTGS2 and ACSL4, and two necroptosis-related proteins, NLRP3 and caspase-1, are upregulated in the advanced stages of atherosclerosis (AS) and are positively correlated with the severity of AS." (PMID 39072329, 2024). "In this case, caspase-1 promoted atherosclerosis by enhancing the inflammatory status of the lesion." (PMID 38824481, 2024). "The five key genes related to three pathways included the SNARE interactions in the vesicular transport pathway (SNAP23, VTI1A), the insulin signaling pathway (IRS2, PRKAR1A), and lipid and atherosclerosis (CASP1)." (PMID 38674428, 2024). "Here, we investigated the role of caspase-1 in foam cell formation in HIV-accelerated atherosclerosis." (PMID 37629052, 2023). "Ethanol activates NLRP3/caspase-1, not only in the cerebral vessel, which leads to early development of atherosclerosis, but also in the brain, which amplifies neuroinflammation." (PMID 36059543, 2022). "Recent studies have shown that nucleotide-binding oligomerization domain-like receptor protein 3 (NLRP3) inflammasomes, which are activated by ox-LDL, aggravate atherosclerosis through caspase-1-induced IL-1β secretion." (PMID 36330745, 2022). "In the coronary tree, upregulation of ASC, caspase-1, and IL-18 was noted in segments with advanced atherosclerosis, together with prevalent NLRP3 inflammasome-positive foam cells around the necrotic core." (PMID 36555579, 2022). "It has been reported that TMAO induced inflammation in human umbilical vein endothelial cells and artery of Apoe gene knockout (Apoe–/–) mice by enhancing the activity of caspase-1 and mitochondrial oxidative stress, which then led to atherosclerosis." (PMID 36420057, 2022). "Our studies reveal that SORBS2 silencing inhibited activation of the NLRP3/ caspase-1/ IL-1β pathway, ultimately blocking the inflammation process in AS, and thus potentially providing protection against hypercholesterolemia and atherosclerosis." (PMID 35590369, 2022). "Consistent with previous findings in an atherosclerosis model, 4μ8C treatment led to a reduction of Casp-1 activity in the hearts of LCWE-injected mice, reflecting reduced NLRP3 inflammasome activation." (PMID 35167493, 2022). "Activation of caspase-1 will trigger pore formation of membrane, DNA fragmentation, and release of IL-1β and IL-18 well known as inflammation response and promoting atherosclerosis." (PMID 36093338, 2022). "This is in line with a recent study reporting that caspase 1-dependent pyroptosis occurs in VSMCs and contributes to the progression of atherosclerosis." (PMID 35625908, 2022).